TNF (tumor necrosis factor)
Diseases named in the same sentence as TNF in open-access papers (continued):
Sharing a sentence is not in itself a finding about the gene and the disease.
Insulin resistance (continued). "To monitor the capacity of TNF-alpha to induce insulin resistance (IR) in each muscle cells population, we measured glucose uptake under control conditions and after 24 h TNF-alpha treatment." (PMID 29968746, 2018). "TNFα neutralization improves peripheral insulin sensitivity in these models, demonstrating a key role of inflammation in the development of insulin resistance." (PMID 29570618, 2018). "Many studies have reported that TNF-α or FFA induce cardiac insulin resistance, and further deteriorate cardiac function via multiple molecular mechanisms." (PMID 28304381, 2017). "Studies have shown that inflammatory factors such as TNF-α, IL-6, and monocyte chemoattractant protein-1 (MCP-1) interfere with the insulin signal transduction pathway and cause insulin resistance." (PMID 29164155, 2017). "Moderate hyperinsulinemia in response to insulin resistance or lowering of TNFα levels within the aorta attenuated vascular damage." (PMID 29163755, 2017). "The proinflammatory factors derived from macrophages (TNF-α, IL-1 β, IL-6) are related to the development of insulin resistance." (PMID 29077020, 2017). "Substantial evidence demonstrates that TNFα perpetuates chronic inflammation leading to insulin resistance, as ablation of TNFα restores insulin sensitivity." (PMID 29018280, 2017). "In insulin-resistant ob/ob mice, metformin improves fatty liver disease, possibly by attenuating hepatic expression of TNF-α, which promotes insulin resistance and plays a role in hepatocarcinogenesis." (PMID 29379799, 2017). "TNF-α, IL-6 and IL-1β, all pro-inflammatory markers, are overproduced in fatty liver and participate in the development of insulin resistance and activate hepatic macrophages called Kupffer cells." (PMID 28555043, 2017). "To verify TNF-α-stimulated PA transcytosis and heart insulin resistance in vivo, we assessed myocardial glucose uptake using a small animal PET with 18F-fluorodeoxyglucose (FDG)." (PMID 28304381, 2017). "BBR inhibited inflammation, ameliorated insulin resistance, and reduced the production of proinflammatory cytokines such as IL-6, IL-17, TNF-α, and interferon-γ (IFNγ) in NOD mice." (PMID 29164155, 2017). "On the other hand, type 2 DM is due to increased peripheral insulin resistance secondary to enhanced production of IL-6 and TNF-α in response to high-fat and/or calorie-rich diet (rich in saturated and trans fats)." (PMID 28824543, 2017). "The role of obesity-related inflammation in the development of insulin resistance was first suggested by experimental studies revealing that TNF-α increase/blocking was able to induce/decrease insulin resistance in in vitro and in vivo models." (PMID 28115795, 2017). "TNF-α and IL-6 are considered the major players in chronic low-grade inflammation and insulin resistance." (PMID 28396851, 2017). "The present study elucidated the remarkable role of TNF-α in increasing PA transport across the endothelium barrier, which in turn facilitates PA-related cardiac insulin resistance." (PMID 28304381, 2017). "Ginsenoside Rb1 reduced free fatty acids in the blood and fat content, improved lipid metabolism and insulin resistance, and inhibited TNF-α, IL-6, and other inflammatory factors in obese mice." (PMID 29164155, 2017). "TNF-α was believed to induce insulin resistance by inhibiting phosphorylation of IRS-1 and Akt substrate 160 on insulin signaling cascade." (PMID 28716139, 2017). "Inflammatory cytokines, such as interleukin 1 (IL1), IL6 and tumor necrosis factor alpha (TNF-α) have been confirmed to be involved in developing insulin resistance." (PMID 29142506, 2017). "Increased AGE/RAGE, ROS, and HbAc1 in nerve fibers activates apoptosis and insulin resistance via activation of NF-κβ and release of TNF-α." (PMID 29163178, 2017). "It has been reported that TNFα directly downregulates adiponectin thus contributing to the development of vascular insulin resistance and to decreased UCP2 levels in the aorta." (PMID 29163755, 2017).
Insulin resistance (continued). "Expression of miR-378 was found to be significantly elevated after TNF-α, IL-6, and leptin stimulation, whose result indicates that miR-378 probably is a novel mediator in the molecular mechanisms related to insulin resistance and obesity." (PMID 29077020, 2017). "A high level of TNF-α is believed to induce insulin resistance and is considered to contribute to the development of diabetes." (PMID 28716139, 2017). "TNF-α is one of the major local regulators in adipose tissue that contributes to insulin resistance and inflammation." (PMID 29085434, 2017). "These immune regulatory cells synthesize and release proinflammatory cytokines such as IL-1, IL-6, and TNF-α which are regarded as the key factors involved in metabolic dysregulation including glucose and lipid disorders and insulin resistance in T2D." (PMID 28396851, 2017). "TNF-α, and cytokines activates NF-κβ and recruit monocytes producing macrophages M1 and M2 that promote β-cell destruction and insulin resistance." (PMID 29163178, 2017). "This M1 predominant state in adipose tissue can lead to an increase in local inflammation and insulin resistance mediated by cytokines such as TNFα." (PMID 29445750, 2017). "It is well described that proinflammatory cytokine tumour necrosis factor α (TNFα) and the adipocytokine adiponectin and leptin play crucial roles in insulin resistance." (PMID 29104874, 2017). "Rosiglitazone improves insulin resistance by reducing the livers' free fatty acid utilization, TNF-α release, and IRS-1Ser307 phosphorylation expression, so we take rosiglitazone as a positive control." (PMID 28630632, 2017). "A previous study found that inflammatory macrophages release TNF-α, inducing insulin resistance in adipocytes, which then secrete more CCL5 and MCP-1 and attract more macrophages that infiltrate into adipose tissue." (PMID 28900399, 2017). "One potential upstream regulator of TNFα and insulin resistance is high mobility group box 1 (HMGB1)." (PMID 28542588, 2017). "Relevantly, TNF-α is a major proinflammatory cytokine implicated in the metabolic syndrome and it is well established that TNF-α induces insulin resistance." (PMID 28265178, 2017). "High-fat diets not only elevated the hepatic free fatty acid levels associated with non-alcoholic fatty liver disease through cellular oxidative stress, but also led to insulin resistance related to hepatic tumor necrosis factor (TNF)-α and interleukin-6." (PMID 29048361, 2017). "Levels of the pro-inflammatory cytokine, TNFα, a potent inhibitor of insulin signaling and therefore a major contributor to insulin resistance, are elevated in obese subjects." (PMID 29104232, 2017). "M1 macrophages act in the production of proinflammatory cytokines, such as IL-1β, IL-6, and TNF-α, which provoke the development of insulin resistance in adipocytes." (PMID 29077020, 2017). "Insulin resistance in adipocytes has been shown to correlate with inflammatory response, especially TNF‐α leading to a low glucose uptake into the cells." (PMID 28572933, 2017). "In an in vitro CMEC and cardiomyocyte co-culture model, we confirmed TNF-α promoted PA-induced insulin resistance and this effect was positively correlated with the amount of PA." (PMID 28304381, 2017). "Since the maternal plasma TNFα level is elevated in PE, GDM, or obese pregnant women, a potential TNFα-dependent inhibition of adiponectin release in insulin resistance in pregnant women, and perhaps the foetus, is likely." (PMID 29104874, 2017). "Activated leukocytes release many kinds of cytokines, including tumor necrosis factor-α, nuclear transcription factor-kappaB, and interleukin, superoxide radicals, and proteases, all of which contribute to insulin resistance, MetS, and atherosclerosis." (PMID 29075331, 2017). "Plasma ceramides have also been shown to correlate with levels of the inflammatory cytokines TNF-alpha and IL6 and have been suggested to be the mediator behind TNF-alpha-induced insulin resistance." (PMID 28545587, 2017).
Insulin resistance (continued). "Blood samples were collected over the 14-week study and analyzed for glucose, lipid profile, and CRP, lipid particles, TNF-α, IL-10, insulin, and insulin resistance (IR)." (PMID 29410955, 2017). "TNF-α is considered a contributing factor for metabolic disturbances such as insulin resistance and dyslipidemia in type 2 diabetes." (PMID 28369107, 2017). "There are a number of reports that focus on typical inflammatory adipokine TNF-α and its involvement in insulin resistance and other actions since the expression of TNF-α was found to be upregulated in the WAT of obese model animals." (PMID 28168013, 2017). "TNFα also plays an important role in the metabolic alterations like altered lipid and carbohydrate metabolism and insulin resistance that are typical of cachexia syndrome." (PMID 29081600, 2017). "A strong positive correlation has been observed between TNF-α mRNA expression levels in fat tissue and the extent of hyperinsulinemia, an indirect marker of insulin resistance." (PMID 28587303, 2017). "A meta-analytic study showed in NAFLD the efficacy of probiotic therapies in terms of aminotransferases, cholesterol and tumor necrosis factor α (TNF-α) reduction and insulin resistance improvement." (PMID 28767077, 2017). "Later studies have shown macrophage infiltration in obese fat tissue and their contribution to pro-inflammatory cytokine production (including TNFα) and insulin resistance." (PMID 29163542, 2017). "During sepsis, inflammatory cytokines in particular IL-6 and TNFα induce a state of insulin resistance." (PMID 28233125, 2017). "In high-fat diet-fed mice, the TNF-α-mediated insulin resistance involves inhibition of the AKT/NO signaling." (PMID 29229986, 2017). "For example, high levels of TNF-α, interleukin-6, and interleukin-8 have all been reported in various diabetic and insulin-resistant state." (PMID 29387832, 2017). "TNF-α protein, encoded by TNF-α gene, is associated with cellular differentiation, proliferation, apoptosis, inflammatory responses, insulin resistance, and tumorigenesis." (PMID 28881857, 2017). "TNF-α stimulates the pro-inflammatory phenotype in adipose tissues leading to the development of insulin resistance and metabolic syndrome." (PMID 28972997, 2017). "The prevention of insulin resistance in heifers treated with TNFα was achieved by treatment with TZD by Kushibiki and collaborators." (PMID 28740504, 2017). "Free fatty acid can also serve as an endogenous signal to stimulate the production of pro-inflammatory mediators, such as TNF-α and IL-6, and inhibition of pro-inflammatory signaling pathways can prevent free fatty acid-induced insulin resistance." (PMID 27213439, 2016). "After binding to its receptors, TNFα can lead to insulin resistance via inhibiting insulin receptor (IR) signaling." (PMID 26877773, 2016). "Oleate, the main lipid component of virgin olive oil, protects against cardiovascular insulin resistance and improves endothelial dysfunction in response to TNF-α." (PMID 27562094, 2016). "Serum levels of these cytokines correlate remarkably well with the presence of insulin resistance, and adipose tissue-derived TNF-α and IL-6 have been shown to regulate hepatic insulin resistance via upregulation of SOCS3, a suppressor of cytokine signaling." (PMID 27247565, 2016). "Bouzakri and Zierath reported that TNF-α leads to insulin resistance by directly targeting muscle insulin signaling." (PMID 27878229, 2016). "The previous studies have also found that TNF-α produced by adipose tissue can induce insulin resistance (IR); these data showed the relationship between inflammatory factors and insulin resistance." (PMID 27965984, 2016). "The literature shows that the development of maternal insulin resistance appears to be responsible for the increase in TNF-α levels from the first stage of prenatal development to the 28th week." (PMID 28018922, 2016).
Insulin resistance (continued). "Currently available data suggest that TNF-α plays a direct role in the development of insulin resistance by decreasing glucose uptake into adipocytes via suppression of insulin receptor activity, AMPK activation, and downregulation of GLUT4 expression." (PMID 27069930, 2016). "Proinflammatory immune mediators, like IL-1β, IL-6, or TNF-α, are important factors in the development of insulin resistance." (PMID 27069930, 2016). "TNF-α is a potent inducer of insulin resistance, whereas IL-5 can activate the eosinophil cells to participate in inflammation." (PMID 27738641, 2016). "Increased inflammatory markers are also a concomitant of insulin resistance onset induced with adiponectin, resistin, and TNFα." (PMID 27147943, 2016). "In 1993, Hotamisligil and colleagues firstly found in diabetic animals that neutralizing tumor necrosis factor (TNF)-α is helpful in ameliorating insulin resistance, indicating the important role of inflammation in the initiation and development of DM." (PMID 27879681, 2016). "Overall, our results revealed that intrauterine hyperglycemia can influence the DNA methylation level in the promoter regions of inflammatory factors involved in insulin resistance, such as TNF-α, and the DNA methylation is intergenerational and inherited." (PMID 26881249, 2016). "TNF-α is significantly observed in adipose cells of obese individuals, and triggers insulin resistance." (PMID 26930407, 2016). "This indicates that the elevated TNF-α levels are directly related to the insulin resistance and androgen excess of PCOS." (PMID 27764100, 2016). "Adipocyte enlargement due to increased accumulation of triglycerides is associated with an increase in the levels of the proinflammatory cytokine TNFα, a decrease of adiponectin, and increased insulin resistance." (PMID 26904104, 2016). "Studies indicated that neutralization of TNF-α activity by an anti-TNF-α monoclonal antibody improves insulin resistance and fatty liver disease in animals." (PMID 27247565, 2016). "On the other hand, cytokines, such as tumor necrosis factor (TNF-α) and resistin, play an important role in cardiovascular risk and insulin resistance." (PMID 27608037, 2016). "A number of these adipokines, such as adiponectin, leptin, TNF-α, resistin, PAI-1, IL-6 and MCP-1, were found to be directly related to insulin resistance and associated morbidities." (PMID 27651836, 2016). "Increased expression/production of TNFα in adipose tissue was observed in obese individuals, and it is playing the vital role in obesity-induced insulin resistance." (PMID 27527213, 2016). "TNF (Tumor Necrosis Factor) has been shown to be a multifunctional pro-inflammatory cytokine, with effects on lipid metabolism, coagulation, insulin resistance, as well as endothelial function." (PMID 27791983, 2016). "For instance, it was shown decades ago that the proinflammatory cytokine tumor necrosis factor alpha (TNFa) induces insulin resistance." (PMID 26751381, 2016). "In fact, artificially induced oxidative stress increased TNF-α production and provoked insulin resistance through reduced GLUT4 expression in adipocytes." (PMID 27023799, 2016). "It is reported that TNF-α is a possible mediator of insulin resistance and diabetes since it inhibits insulin signaling and impairs its secretion." (PMID 27478850, 2016). "TNF-α is a major mediator of chronic inflammation and insulin resistance, and neutralization of TNF–α significantly improves insulin sensitivity." (PMID 27716232, 2016). "Previous findings showed that antioxidant content of Kaempferol reduced IL-1β, TNF-α, and kaempferol was also reported to significantly decrease the fasting blood glucose and improve insulin resistance." (PMID 27527213, 2016). "The JNK and IKK-β pathways are activated by ROS and various other factors including the inflammatory cytokines such as TNF-α, IL-6, and IL-1beta which are involved in the development of insulin resistance found in type 2 diabetes." (PMID 27034691, 2016).
Insulin resistance (continued). "TNF-α, ROS and free fatty acids activate inflammatory pathways and modulate the expression of numerous genes involved in insulin resistance." (PMID 27809851, 2016). "Similar results were observed in whole body Wnt5a knockout mice, which showed that Wnt5a ablation attenuated high-fat/high-sucrose (HFHS)-induced insulin resistance, and these mice displayed decreased expression of TNF-α, CCL2, and IL-6 in adipose tissue." (PMID 27608847, 2016). "Leptin overexpression was found responsible for TNF-α and IL-6-related chronic inflammation, insulin resistance, liver fibrosis, and HCC development." (PMID 27703473, 2016). "C2-ceramide, a short-chain ceramide analog, mimicked TNF-α to induce insulin resistance, decrease GLUT4 gene expression, and completely preclude insulin-stimulated glucose uptake and insulin-induced GLUT4 translocation to plasma membrane." (PMID 26903879, 2016). "Tumor necrosis factor (TNF-α), which plays an important role in insulin resistance through inhibition of the tyrosine kinase activity of the insulin receptor, has recently gained attention for its potential value." (PMID 27089331, 2016). "The GDM animal model showed signs of insulin resistance where expressions of both proinflammatory cytokines (IL-6 and TNF-α), PCK-1, and serum CRP level were higher than control." (PMID 27379252, 2016). "In mice, HHcy promotes insulin resistance by directly inducing the expression and secretion of TNF-α and resistin." (PMID 27608037, 2016). "It has been reported that insulin sensitivity can be reduced by stimulating the secretion of free fatty acids, tumor necrosis factor α, and resistin from enlarged adipocytes, and there is a correlation between insulin resistance and the visceral fat load." (PMID 26767080, 2016). "During insulin resistance, TNF‐α increases gluconeogenesis, lipolysis and proteolysis, which result in decreased protein, lipid and glycogen synthesis." (PMID 26843513, 2016). "Similar data were obtained using sodium salicylate, which was shown to reverse insulin resistance via inhibition of TNF-α-mediated Ikkβ-driven inflammatory responses." (PMID 27514532, 2016). "So elevated TNF-α levels are related to the insulin resistance and androgen status in women with PCOS." (PMID 27764100, 2016). "TNFα depletion in ob/ob genetic or diet-induced obese mice reduces insulin resistance and improves insulin signaling in adipose tissue and muscle." (PMID 28025491, 2016). "WT and Tnfa−/− mice injected with IL-1β had similar IL-1β induction, with a greater induction of TNF-α and subsequent insulin resistance in the WT mice, demonstrating the effect of TNF-α induction by IL-1β." (PMID 27128935, 2016). "The impact of riboflavin on cytokine expression and release is evidenced by a significant reduction in the TNFα level, considered to be one of the main cytokines related to the development of insulin resistance." (PMID 27983705, 2016). "M1 macrophages, which represent a pro-inflammatory state, can secrete inflammatory cytokines such as tumor necrosis factor (TNF)-α, interleukin-6 (IL-6) and IL-1β that interfere with insulin signaling, and cause adipocyte dysfunction and insulin resistance." (PMID 27878229, 2016). "Although various studies demonstrated a crosstalk between TNF-α and insulin resistance, the mechanisms involved remain to be elucidated." (PMID 27562094, 2016). "Critically ill patients demonstrate elevated levels of TNF and IL-6 and these patients and T2D share phenotypical similarities such as hyperglycemia, insulin resistance, and systemic inflammation." (PMID 27148273, 2016). "Targeting TNF-α has been suggested to be a potential therapeutic method for insulin resistance and type 2 diabetes." (PMID 27324794, 2016). "Various proinflammatory cytokines such as tumor necrosis factor-α (TNF-α), interleukin-6 (IL-6), and interleukin-1β (IL-1β) often participate in the pathogenesis of MS and insulin resistance." (PMID 26728949, 2016).